INS (insulin)
Diseases named in the same sentence as INS in open-access papers (continued):
Sharing a sentence is not in itself a finding about the gene and the disease.
type 2 diabetes (continued). "The findings from this study confirm good psychometric properties of the 20-item insulin treatment appraisal scale (ITAS) in both insulin naïve and insulin-treated type 2 diabetes patients." (PMID 18096074, 2007). "Improvement of insulin sensitivity by acarbose has been shown with hyperglycaemic clamp measurements in elderly patients with type 2 diabetes." (PMID 17697384, 2007). "As with patients with type 2 diabetes, the insulin-sensitizing effect of PIO persisted several weeks after the drug was stopped in PIO-treated individuals." (PMID 17479164, 2007). "Basal-prandial therapy using newer insulin formulations, such as long- and rapid-acting insulin analogs, can be relatively simple to use in patients with type 2 diabetes and is an appropriate methodology for application by primary care clinicians." (PMID 17448241, 2007). "Basal-prandial insulin therapy provides a physiologic approach to the treatment of patients with type 2 diabetes." (PMID 17448241, 2007). "Prospective studies are warranted to determine the extent to which attitudinal changes towards insulin therapy occur in type 2 diabetes patients after insulin initiation." (PMID 18096074, 2007). "A stepwise approach to basal-prandial insulin therapy in patients with type 2 diabetes allows treatment to be advanced as the disease progresses to minimize the risk of complications." (PMID 17448241, 2007). "Understanding the relative contributions of insulin resistance and insulin secretion to the major consequences of type 2 diabetes, such as the development of CHD and stroke, is important for developing better-targeted therapeutics." (PMID 17760500, 2007). "Failure of insulin secretion in patients with Type 2 diabetes and IGT is characterized by decreased first-phase glucose-induced insulin secretion, delayed hyperinsulinaemia and the late development of failure of insulin synthesis." (PMID 17257277, 2007). "ob/ob Mice are well suited for studies on the interaction between leptin and insulin, and for studies on initial aspects of metabolic disturbances leading to type-2 diabetes." (PMID 17619751, 2007). "Insulin-naive patients with type 2 diabetes who fail to achieve or maintain adequate glycemic control on OADs over 3–6 months should be started on basal insulin therapy." (PMID 17448241, 2007). "Eventually, the insulin-producing cells in the pancreas start to malfunction, insulin secretion decreases, and type 2 diabetes is the result." (PMID 17760500, 2007). "The results from this study suggest that the ITAS is a valid self-report instrument that would seem useful in people with type 2 diabetes who have difficulty accepting insulin treatment." (PMID 18096074, 2007). "In obese type 2 diabetics, insulin-sensitizing drugs known as thiazolidinediones (TZDs) also have been reported to reduce visceral fat and improve insulin sensitivity." (PMID 17479164, 2007). "Modern insulin therapy regimens in type 1 and type 2 diabetes aim to mimick the patterns of physiologic insulin secretion." (PMID 18030331, 2007). "Recent consensus conference recommendations from the American College of Endocrinology indicate that glycemic targets can be effectively achieved by basal insulin plus an OAD or basal-prandial insulin regimens in type 2 diabetes." (PMID 17448241, 2007). "We report here that serotonin 2C receptor (5-HT2CR) agonists, typically investigated for their anorectic properties, significantly improve glucose tolerance and reduce plasma insulin in murine models of obesity and type 2 diabetes." (PMID 17983585, 2007). "RXR-specificligands have potent glucose-lowering, insulin-sensitizing, andantiobesity effects in animal models of obesity, insulinresistance, and type 2 diabetes." (PMID 17497022, 2007). "Specifically, it has been reported that improved blood glucose control with insulin or sulfonylurea therapy decreased the progression of microvascular complications in patients with type 2 diabetes." (PMID 17727695, 2007).
type 2 diabetes (continued). "The majority of patients (75.2%) recruited for the SHIP Premix study had type 2 diabetes and had been treated with insulin for five years on average." (PMID 17727695, 2007). "Contribution to the evidence: Other studies have shown that PIO administration has beneficial effects on insulin sensitivity in people with type 2 diabetes." (PMID 17479164, 2007). "The SHIP© questionnaire is a reliable and valid instrument that is promising for assessing the intentions of type 1 and type 2 diabetes patients regarding insulin therapy, and the reasons for their behaviour." (PMID 17727695, 2007). "Modified analogs of lipid lowering drugs were found to lower both glucose and insulin levels in rodent models of type 2 diabetes secondary to improved insulin sensitivity." (PMID 19936080, 2007). "Patients with Type 2 diabetes show failure of glucose-induced insulin secretion, which is characterized by a decrease in the first phase of glucose-induced insulin secretion, delayed hyperinsulinaemia and, latterly, failure of insulin synthesis." (PMID 17257277, 2007). "In this study, we studied the effects of telmisartan on insulin sensitivity in KK-Ay mice, an obese type 2 diabetic animal." (PMID 23675001, 2006). "There is also a clinical evidence indicating that intensive insulin treatment in Type 2 diabetes improve β-cell function." (PMID 16448577, 2006). "Using electronic pharmacy databases, we randomly selected 338 veterans with insulin-treated type 2 diabetes." (PMID 16716235, 2006). "Insulin is the drug of choice in controlling hyperglycaemic state in Type 1 and sometimes for Type 2 diabetes." (PMID 16448577, 2006). "Those individuals with type 2 diabetes who used insulin had higher testing supply costs than those on oral antidiabetic medication alone ($359 vs $131; p < 0.001)." (PMID 17164006, 2006). "Some studies have reported that patients with type 2 diabetes on oral medications have greater HRQL than patients on insulin." (PMID 17034640, 2006). "In this study, we studied the effects of telmisartan on insulin sensitivity in KK-Ay mice, an obese type 2 diabetic animal model." (PMID 23675001, 2006). "Disrupted insulin secretion is observed prior to onset of type 2 diabetes, and when combined with the development of insulin resistance in peripheral tissues, results in chronic hyperglycaemia." (PMID 16464129, 2006). "Current data suggest that UCP2 plays a role in the metabolic syndrome through down-regulation of insulin secretion and development of type-2 diabetes." (PMID 16968550, 2006). "In normal subjects, the insulin increase was only 30% of that to 50 g glucose, but in people with type 2 diabetes, it was equal, i.e. 100%." (PMID 16556307, 2006). "Those individuals with type 2 diabetes using insulin, alone or in combination with oral medication, had higher testing supply costs than those on oral antidiabetic medication ($359 vs $131; p < 0.001)." (PMID 17164006, 2006). "Subsequently we demonstrated that dietary protein acts synergistically with ingested glucose to increase insulin secretion and reduce the blood glucose response to the ingested glucose in people with type 2 diabetes." (PMID 16556307, 2006). "UCP2 is a regulator of insulin secretion and it is proposed that increased expression of UCP2 in pancreatic β-cells results in chronic down-regulation of glucose stimulated insulin secretion leading to β-cell dysfunction and the development of type-2 diabetes." (PMID 16968550, 2006). "From these and other studies we concluded that in people with type 2 diabetes, dietary protein is a potent insulin secretagogue." (PMID 16556307, 2006). "Adults with type 2 diabetes who live farther from their source of primary care are less likely to use insulin." (PMID 16872541, 2006). "Adults with type 2 diabetes who live farther from their source of primary care are significantly less likely to use insulin." (PMID 16872541, 2006).
type 2 diabetes (continued). "With this and other information, several years ago, we determined the glucose and insulin responses to 50 g of protein given in the form of lean beef to 8 normal subjects and 7 subjects with type 2 diabetes." (PMID 16556307, 2006). "When diet alone cannot effectively control the type 2 diabetic conditions, medical interventions, such as insulin injections or dispensing hypoglycaemic pills, are usually the next step of managing type 2 diabetes mellitus." (PMID 15644138, 2005). "Type 2 diabetes results from the metabolic problem that is related to certain tissue resistance to insulin action and to the inability of the pancreas to appropriately regulate the quantity of insulin for glucose metabolism." (PMID 15644138, 2005). "This study will make an important contribution to the evidence-base for the use of blood glucose self-monitoring in non-insulin using patients with type 2 diabetes." (PMID 15960852, 2005). "The inhibitory effect of chronically elevated plasma FFA is more prominent in individuals with a genetic predisposition to develop type 2 diabetes, thus a reduction in the plasma FFA concentration in type 2 diabetes improves insulin secretion." (PMID 15634355, 2005). "Type 2 diabetes is characterized by the body's inability to produce enough insulin or use insulin properly." (PMID 16263044, 2005). "During the 1990's there were steady increases in the prevalence of diet only, oral treatment only and insulin treated type 2 diabetes." (PMID 15784133, 2005). "This autonomic impairment is major in insulin resistant offsprings than non insulin resistant offsprings of type 2 diabetic patients." (PMID 16197556, 2005). "Type 2 diabetes is treated with diet, physical activity, and often oral medications, insulin injections, or both." (PMID 16263044, 2005). "Clinical data have also revealed that the insulin sensitizing agent troglitazone is efficacious in both β-cell preservation and delaying the onset of type 2 diabetes." (PMID 16232315, 2005). "In a 14-day inpatient feeding study, 10 participants with type 2 diabetes experienced improvements in hemoglobin A1c and insulin sensitivity as measured by the euglycemic hyperinsulinemic clamp method." (PMID 16318637, 2005). "Patients with type 2 diabetes who require insulin and who are scheduled for surgery should be managed similarly to patients with type 1 diabetes." (PMID 15916471, 2005). "In type 2 diabetes the triglyceride level is increased, which is due to multiple factors related to insulin and carbohydrate metabolism, LPL activity, CETP activity..." (PMID 15636639, 2005). "Mitochondrial dysfunctions have been reported in the muscle in type 2 diabetes and in age-related insulin resistance, suggesting a link between insulin action and oxidative capacity in humans." (PMID 16300674, 2005). "Disturbance of this function is thought to play a major role in the hyperglycemia of type 2 diabetes and in other insulin-resistant states." (PMID 16300674, 2005). "In that much smaller study, the prevalence of type 2 diabetes was 20.3 per 1000 in males and 16.7 per 1000 in females in 1997, of whom 34% were treated by diet only, 53% were oral only and 14% were on insulin." (PMID 15784133, 2005). "Type 2 diabetes mellitus (T2D) and the metabolic syndrome are characterized by resistance to the action of insulin in peripheral tissues, including skeletal muscle, liver, and adipose." (PMID 15491498, 2004). "In summary, in single meal studies in people with type 2 diabetes, dietary protein strongly stimulated insulin secretion and decreased the plasma glucose response to ingested glucose." (PMID 15507157, 2004). "Esters of succinic acid are potent insulin secretagogues,and have been proposed as novel antidiabeticagents for type 2 diabetes." (PMID 12369722, 2001). "Chlorpropamide is a medication used to treat type 2 diabetes by increasing pancreatic insulin secretion." (PMID 15706798, 1998).
type 2 diabetes (continued). "Type 2 diabetes mellitus (T2DM) is an increasingly common metabolic condition characterized by an inability to regulate plasma glucose levels because of tissue insensitivity to insulin and beta cell dysfunction." (PMID 40804611, 2026). "Type 2 diabetes (T2D) is a disease characterized by hyperglycemia resulting from a relative or absolute impairment in insulin secretion, accompanied by varying degrees of resistance to the action of insulin." (PMID 41601512, 2026). "Vaspin, on the other hand, may have an inhibitory effect on the development of type 2 diabetes and metabolic syndrome by increasing insulin sensitivity." (PMID 41970985, 2026). "Mbd2 and Tnip1 have significant relationships between DNAm variation and insulin type 2 diabetes." (PMID 41432313, 2026). "Similarly, inhibition of ROCK1/2 activity in type 2 diabetes-induced pluripotent stem cell-derived hepatocytes restored aspects of insulin signaling." (PMID 41535231, 2026). "Moreover, mir-24 has also been found to inhibit β-cell proliferation and insulin secretion by targeting maturity-onset diabetes of the young (MODY) genes, Hnf1α and Neurod1." (PMID 41384367, 2026). "Delineating the signaling cascades through which LRRC8A modulates insulin secretion and β-cell viability could reveal novel targets for early intervention in type 2 diabetes pathogenesis." (PMID 41439137, 2026). "Treatment of patients with type 2 diabetes (T2D) with insulin or sulphonylurea therapy in an intensive therapeutic regime may lead to hypoglycemia, which may result in loss of consciousness, seizure, coma and even death." (PMID 41596469, 2026). "One group has reported that increased β cell expression of HRD1 (such as may occur in type 2 diabetes or in mouse models of the disease) triggers impaired insulin secretion, whereas impaired ERAD capacity by HRD1 knockdown (KD) improves blood glucose control." (PMID 41252202, 2026). "Rare monogenic forms, including maturity-onset diabetes of the young and neonatal diabetes, arise from highly penetrant single-gene defects that directly impair transcriptional regulation, glucose sensing, insulin biosynthesis, or stimulus-secretion coupling." (PMID 41900917, 2026). "Clinical trials have validated the favorable outcomes of equol and its precursors, particularly in postmenopausal women with type 2 diabetes, leading to a significant decrease in fasting insulin levels, enhanced insulin sensitivity, and sustained blood glucose stability over the long term." (PMID 41523283, 2026). "GLP1’s beneficial effect on weight and insulin sensitivity as well as the reduced frequency of administration support the rationale for considering its usage as monotherapy in patients with new-onset type 2 diabetes." (PMID 41204644, 2026). "Agents incorporating GIPR agonism might optimally benefit patients with type 2 diabetes through improvements in both glucose tolerance and insulin sensitivity." (PMID 41287212, 2026). "Partial downregulation of pancreatic endoplasmic reticulum kinase (PERK) activity recovered insulin content in human islets exposed to glucolipotoxicity (GLT), resulting in improved insulin secretion and glucose-lowering effects in a mouse model of type 2 diabetes." (PMID 42155730, 2026). "Therefore, polymorphisms in KCNK17 that increase TALK-2 activity or expression would be predicted to increase type 2 diabetes risk by blunting beta cell glucose-stimulated Ca2+ influx, limiting GSIS, promoting Ca2+ER leak and elevating basal insulin secretion." (PMID 41739147, 2026). "Dysfunctional adipose tissue is characterized by altered adipokine secretion, impaired insulin sensitivity, and chronic low-grade inflammation, all of which contribute to obesity-related comorbidities such as type 2 diabetes, cardiovascular disease, and certain cancers." (PMID 41596407, 2026).
type 2 diabetes (continued). "Previous research has shown that whether aerobic exercise precedes resistance or vice versa, both sequences improve insulin sensitivity through enhanced glucose absorption and increased insulin receptor activity in patients with type 2 diabetes." (PMID 41499584, 2026). "Insulin therapy is central to the management of type 1 diabetes and is frequently required in advanced type 2 diabetes, with conventional regimens involving multiple daily injections that may negatively impact adherence." (PMID 42254168, 2026). "This metabolic profile may lower the long-term burden of type 2 diabetes by preserving beta cell function and improving insulin sensitivity." (PMID 41107618, 2026). "However, the fact that all participants of our cohort were long-term insulin dependent and clinically presented like type 1 diabetes makes the diagnosis of classic type 2 diabetes less probable compared with KPD." (PMID 41175199, 2026). "BACKGROUND: This study explored the effect of blackberry fruit extract (BFE) and metformin (Met) on biochemical markers, redox parameters, and the downstream insulin signaling pathway in a high-fat diet (HFD) + streptozotocin (STZ) induced Type 2 Diabetic Rat model." (PMID 41931160, 2026). "Therefore, this study aims to investigate how the sequence of aerobic and resistance training within a concurrent exercise program affects insulin resistance, fasting glucose, and blood pressure markers in adults with type II diabetes." (PMID 41499584, 2026). "When cells become insulin-resistant, glucose accumulates in the blood, which may lead to type 2 diabetes." (PMID 40168333, 2025). "Dynamic changes in PTM patterns are therefore likely to be critical molecular switches that determine whether insulin resistant tissues and pancreatic beta cells remain in a compensated state or progress toward overt beta cell failure and type 2 diabetes." (PMID 41373704, 2025). "Type 2 diabetes and obesity are two syndromes that can be cured by anthocyanins and ellagic acid's capability to decrease inflammation in adipose tissue as well as improve insulin sensitivity." (PMID 40417739, 2025). "Furthermore, type 2 diabetes treated with insulin was more likely to develop AVS than those only treated with oral glucose-lowering medications." (PMID 40356984, 2025). "While glucose tolerance and insulin sensitivity remained unchanged, combination therapy restored insulin secretion, increased β-cell mass, and reduced apoptosis, suggesting a protective role in type 2 diabetes treatment." (PMID 40822946, 2025). "His history of Type II diabetes suggested insulin or insulin secretagogue involvement." (PMID 41368518, 2025). "Genetic evidence suggests that shared pathways exist between depression and insulin-related diseases, such as metabolic syndrome and type 2 diabetes, with insulin resistance potentially serving as a metabolic subtype of depression and offering a target for personalized treatments." (PMID 40362522, 2025). "This post hoc analysis of five separate randomised trials (ONWARDS 1–5) aimed to examine physical activity-attributed hypoglycaemic episodes in adults with type 2 diabetes receiving either once-weekly basal insulin icodec (herein referred to as ‘icodec’) or once-daily basal insulins." (PMID 40186685, 2025). "This study aimed to investigate the effect of 8 weeks of high intensity interval training (HIIT) on insulin resistance through liver gluconeogenesis, lipolysis, inflammation, oxidative stress, and lipogenesis in Type 2 diabetic rats with a special focus on the role of SPX." (PMID 40841811, 2025). "Moreover, it influences insulin sensitivity and acts as a mediator of inflammation in adipose and hepatic tissues, potentially linking obesity to the pathogenesis of type 2 diabetes." (PMID 40725024, 2025).